S100A8 (S100 calcium binding protein A8)
Diseases named in the same sentence as S100A8 in open-access papers (continued):
Sharing a sentence is not in itself a finding about the gene and the disease.
tumor (continued). "S100A8/A9 release was evident and detectable at an early stage of the metastatic process before tumor cells seeded in the lungs of 4T1.2 tumor-bearing mice and presented along with increased numbers of MDSC-like cells and Treg." (PMID 28744322, 2017). "This study provides the first evidence that S100A8/A9 can be used as a non-invasive imaging marker, for the establishment of a tumor-permissive, immunosuppressive environment in target organs of metastasis." (PMID 28744322, 2017). "MSCs contact enhanced naïve HME cells CM and exacerbated IRISOE tumor cells CM ability to induce THP1-macrophages to secrete S100A8 (compare black to white bars)." (PMID 29262555, 2017). "MDSC accumulation in the primary tumour and recruitment to pre-metastatic lungs 7 is mediated by the protein heterodimer S100A8/A9 8, members of the S100 protein family." (PMID 28744322, 2017). "The tumor suppressor activity represents a novel function of intracellular S100A8/A9 in addition to conferring resistance to invasion of epithelial cells by invasive pathogens and anti-inflammatory functions." (PMID 26883112, 2016). "Mice inoculated with S100A8-shRNA- or S100A9-shRNA-transfected MC38 or LLC cells had considerably reduced metastatic tumor burden compared with controls." (PMID 27086923, 2016). "In this study, we show that tumor-infiltrating monocytes/macrophages regulate the expression of S100A8 and S100A9 in cancer cells." (PMID 27086923, 2016). "RAGE (receptor for advanced glycation end products) is the principal receptor of S100A8/A9 on the surface of tumour cells." (PMID 26880885, 2016). "In TGCA, the data are insufficient to report HNSCC survival and patient tumor characteristics when only S100A8 or S100A9 was downregulated." (PMID 26883112, 2016). "On examination of the hematoxylin- and eosin-stained liver sections, tumor colonies appeared to be better demarcated, with well-circumscribed borders in the S100A8 and S100A9 knockdown groups compared with controls." (PMID 27086923, 2016). "Carcinomas of these tissues show decreased S100A8/A9 protein complex and reduction in S100A8/A9 is correlated with poor tumor differentiation and increased carcinoma growth and invasiveness." (PMID 26883112, 2016). "More invasive extensions of the tumor colonies into the adjacent liver were evident in controls compared with the S100A8 or S100A9 knockdown cells." (PMID 27086923, 2016). "We now report for the first time that intracellular S100A8/A9 functions as a tumor suppressor in vivo." (PMID 26883112, 2016). "Collectively, these data suggest that monocytes/macrophages in liver metastases induced tumor cell proliferation, migration and invasion, and upregulated S100a8 and S100a9 expression through TNFα-induced ERK activation." (PMID 27086923, 2016). "We also examined the effect of S100A8 on tumorigenicity in vivo using subcutaneously tumor model in nude mice." (PMID 27462864, 2016). "Pro-tumor neutrophils upregulate the expression of pro-metastatic proteins, e.g., Bv8, S100A8, and S100A9, but also VEGF and MMP9 in pre-metastatic lungs of IFN-deficient mice." (PMID 28066438, 2016). "In response to conditioned media from tumor-infiltrating monocytes/macrophages, cancer cells upregulated S100a8 and S100a9 messenger RNA expression through an extracellular signal-related kinase-dependent mechanism." (PMID 27086923, 2016). "In summary, our data demonstrated that S100A8 were frequently hypermethylated in non-tumor tissues but hypomethylated in HCC tissues." (PMID 27462864, 2016). "To verify this impression, we compared the area of the invasion front of each individual tumor colony and found the invasive areas to be significantly reduced when S100A8 and S100A9 were downregulated in both MC38 and LLC cells." (PMID 27086923, 2016). "We demonstrate that tumor-infiltrating monocytes/macrophages induced S100A8 and S100A9 expression in cancer cells to promote migration and invasion." (PMID 27086923, 2016).
tumor (continued). "Staining area and intensity of MMP2 and MMP9 in the MC38 and LLC tumor colonies were notably decreased in the S100A8 and S100A9 knockdown groups compared with controls." (PMID 27086923, 2016). "S100A8 ablation in mice can decrease cell proliferation, leading to significant reduction of tumor size." (PMID 27462864, 2016). "This study implicates S100A8 and S100A9 as important mediators of tumor cell aggressiveness, and highlights the therapeutic potential of S100A8 and S100A9 for interference of metastasis." (PMID 27086923, 2016). "Since expression levels appeared unaffected by the tumor stage, suppression of S100A8 and S100A9 expression is likely an early event in the pathogenesis of HNSCC and is independent of HPV status and copy number gains." (PMID 26883112, 2016). "Upon ectopic over-expression of S100A8/A9, the cancer phenotype of S100A8/A9-negative carcinoma cells was suppressed in vitro and tumor growth in vivo was significantly decreased." (PMID 26883112, 2016). "In our model, tumor-derived S100A8 and S100A9 have distinct effects apart from myeloid cell recruitment, one of which is to promote cancer cell invasion." (PMID 27086923, 2016). "Culture of MC38 and LLC cancer cells in conditioned media from tumor-infiltrating monocytes/macrophages and granulocytes induced S100a8 and S100a9 mRNA expression." (PMID 27086923, 2016). "Comparison of tumor colonizes of different sizes in the three experimental groups also showed markedly reduced invasive areas in the S100A8 and S100A9 knockdown groups." (PMID 27086923, 2016). "Normal and SCC-derived keratinocytes showed distinct phosphorylation of JNK after S100A8/A9 stimulation, which is probably due to a different response to S100A8/A9, based on their origin (tumor vs. normal cells)." (PMID 25811984, 2015). "Most genes encoding S100 proteins are clustered on a region of human chromosome 1q21 that is prone to chromosomal rearrangements, suggesting a link between S100A8/A9 proteins and metastasis and tumor formation." (PMID 25789858, 2015). "Here, we present the receptor for advanced glycation end products (RAGE) and S100A8/A9 as important factors driving normal and tumor keratinocyte proliferation." (PMID 25811984, 2015). "Through TCGA analysis, it was determined that the mRNA levels of S100A8 and S100A9 genes were associated with RCC tumor T stage, which demonstrated that a higher expression indicated a higher stage." (PMID 25673070, 2015). "The in vivo source of S100A8/A9 in tumor tissue is tumor cells and myeloid cells such as neutrophils." (PMID 26625258, 2015). "It has been reported that primary tumors secrete soluble factors, which induce expression of S100A8 in the endothelial cells prior to tumor metastasis." (PMID 25789858, 2015). "Following multivariate analysis adjusting for tumor size, lymph node status, differentiation and age, S100A8 was still statistically significant (P = 0.013 - HR (95% CI) = 0.11 (0.013-0.92))." (PMID 24885002, 2014). "Combining S100A8 in a predictive model for OS with tumor size, lymph node status, differentiation and age improved outcome prediction significantly from 0.605 to 0.833." (PMID 24885002, 2014). "Several extrinsic factors previously reported to be associated with the tumor microenvironment were identified, including GCSF, THBS1, S100A8/A9, CCL2, TNF and TNFSF11." (PMID 25593989, 2014). "So far, a limited number of studies have reported correlation between increased expression of S100A8/A9 and parameters such as tumor differentiation, metastasis, tumor size, and Dukes stage." (PMID 25371673, 2014). "Inclusion of S100A8 protein expression patterns in multivariate models together with tumor size, node status, and age significantly improved OS prediction." (PMID 24885002, 2014). "We therefore studied the effects of S100A8, S100A9 and the S100A8/A9 complex, but also of NT-S100A8, on critical aspects of tumor biology, namely intracellular signaling, cell proliferation and EMT." (PMID 24670043, 2014).
tumor (continued). "When released, S100A8/A9 can signal through the receptor for advanced glycation end products (RAGE) and toll-like receptor 4 (TLR4) to promote tumor-associated inflammation and progression of advanced stage adenocarcinomas and colitis-associated cancer." (PMID 23874958, 2013). "Recently, the over-expression of S100A8 and S100A9 has been observed in many tumor cells, and is associated with poor cell differentiation in some cancers of glandular cell origin." (PMID 23637971, 2013). "Among the complex network of cytokines and inflammatory molecules at the tumor stroma interface that fosters MDSCs, the S100A8 and S100A9 proteins, expressed by both stromal and tumor cells, appear relevant in the PDAC setting." (PMID 23359812, 2013). "The results showed that MDSCs from IL-17−/− tumor-bearing mice expressed lower levels of Arg-1, MMP9, and S100A8 than those from wild-type tumor-bearing mice." (PMID 24453427, 2013). "S100A8 and S100A9, two members of the S100 protein family, have been reported in association with the tumor cell differentiation and tumor progression." (PMID 23637971, 2013). "In conclusion, this data demonstrates that expression of S100A8 and S100A9 in tumor cells is associated with differentiation, Dukes stage and lymph node metastasis in CRC." (PMID 23637971, 2013). "The tumor-promoting function of MDSC is associated with increased activities of Arg-1, MMP9, and S100A8." (PMID 24453427, 2013). "Here, we investigated the clinical significances of S100A8 and S100A9 in tumor cells of CRC and their underlying molecular mechanisms." (PMID 23637971, 2013). "S100A8/S100A9 expression is increased in patients with various tumours, being involved in invasion and migration processes." (PMID 22673103, 2012). "We propose that S100A8/A9, and perhaps also other S100A proteins, either produced by tumor cells or by infiltrating inflammatory cells, promote neovascularization in tumor mass by promoting endothelial cells behavior." (PMID 22685372, 2012). "S100A8 gene is one of the important inflammation factors, which has the ability to promote tumor cell invasion." (PMID 22139384, 2012). "At low concentrations S100A8/A9 complexes promote tumor cell growth and tumor cell migration, while at high concentrations apoptotic effects on tumor cells were observed." (PMID 22489132, 2012). "In conclusion, miR-24 was down-regulated in LSCC, and functions as a tumor suppressor in Hep2 cells partly through targeting the S100A8 gene." (PMID 22139384, 2012). "After preparation of the target tissue to accept the malignant cells, tumor cells mimic Mac-1+ myeloid cells in response to S100A8/A9 chemotactic signaling and they migrate to the lung." (PMID 23166536, 2012). "The predicted enhancer effect of S100A8/A9 on tumor development was also confirmed by a couple of experimental studies." (PMID 22685372, 2012). "In this context S100A8/A9 was shown to promote pre-metastatic niche formation in the lungs of tumor-bearing mice." (PMID 23241281, 2012). "Taking into account the fact that many tumors produce S100A8/A9 to a certain extent, we proposed that S100A8/A9, from either tumor cells or infiltrating leukocytes, promote the transformed cells to create a blood vessel supply for themselves." (PMID 22685372, 2012). "Next, we quantified the number of S100A8-positive inflammatory cells in each tumor tissue for S100A9." (PMID 22838504, 2012). "We next sought to identify a gene expression signature that directly correlated with S100A8 expression levels during disease progression and then use that signature to predict the likelihood of tumor progression." (PMID 20096140, 2010). "As a transcription factor, E2F5 may participate in shaping the LSCC tumor microenvironment by directly or indirectly regulating the expression of NETs hallmark genes (e.g., S100A8/A9, LCN2), thereby influencing tumor progression." (PMID 41488283, 2026).
tumor (continued). "Moreover, IHC analysis demonstrated reduced staining intensity of S100A8/A9 in the W146-treated PDX tumor." (PMID 41513624, 2026). "A previous study suggested that the release of S100A8/A9 proteins and lipids modified by neutrophils can induce reactivation of dormant tumor cells (cancer stem-like cells), further emphasizing the importance of S100A8/A9 proteins in the TME for cancer development and recurrence." (PMID 39796176, 2025). "In a model of smoke-induced lung carcinogenesis, silencing S100A8/A9 with siRNA or silencing RAGE resulted in decreased tumor growth and proinflammatory signaling, with findings suggesting that this pathway sensitizes immune responses to facilitate tumor growth." (PMID 41188771, 2025). "However, S100A8/9+ neutrophils were now observed within the boundary of tumor metastases, and in liver metastases S100A8/9+ neutrophils were observed within the tumor bed near F4/80+ TAMs." (PMID 40568104, 2025). "Interestingly, we observed that Ly6G+ S100A8/9+ neutrophils post triple combination surrounded Vim+ CD44+ tumor cells within the liver." (PMID 40568104, 2025). "Notably, S100A8 is expressed in both immune and tumor cells, and its overexpression has been reported in multiple solid tumors and is consistently associated with poor survival." (PMID 41303754, 2025). "Studies have shown that the regulatory effect of S100A8/A9 on the activity of tumor cells depends on their concentration: at high concentrations, S100A8/A9 inhibit tumor cell growth and promote their apoptosis, whereas at low concentrations, they exhibit the opposite effect." (PMID 40270593, 2025). "Moreover, S100A8 can drive monocyte differentiation into M2 macrophages, further sustaining the immunosuppressive tumor microenvironment and facilitating metastasis." (PMID 40963634, 2025). "Additionally, neutrophils gather in premetastatic niches via CXCR2 or CXCR4-dependent mechanism and release oncostatin M, elastase, and S100A8/S100A9, which causes tumor cell proliferation." (PMID 40016853, 2025). "S100A8/A9, expressed on tumor cells, was considered a neutrophil marker solely in the stroma." (PMID 40721446, 2025). "By clarifying whether tumor-intrinsic or immune-related S100A8 expression carries greater clinical relevance, we aimed to explore the potential of S100A8 as a prognostic biomarker in EC." (PMID 41303754, 2025). "Functional studies suggest that S100A8 modulates tumor growth and sensitivity to chemotherapy, while its expression in immune cells may shape the tumor microenvironment and correlate with clinical outcomes." (PMID 41303754, 2025). "Indeed, pharmacologic or genetic inhibition of S100A8/A9-RAGE receptor signaling blocked nicotine's tumor-promoting effects." (PMID 39856330, 2025). "Interestingly, the inhibition of S100A8/A9 with chemical inhibitors decreased tumor burden in the AOM/DSS-induced mouse model of CAC." (PMID 39425000, 2025). "MCAM has also been described as a co‐receptor for several growth factor receptors such as VEGFR2 or PDGFR‐β or inflammatory mediators such as S100A8/A9, and may thereby promote cell growth and simulate tumour vascularisation." (PMID 39945026, 2025). "Similarly, S100A8/A9 proteins, which are alarmins released by tumor cells, facilitate the recruitment and accumulation of MDSCs within the TME by binding to receptors such as RAGE and TLR4, thereby promoting their survival and expansion." (PMID 41181705, 2025). "In a variety of tumors, S100A9 forms a heterodimer with S100A8, S100A8/A9, which interferes with the tumor microenvironment and metabolism, promotes tumorigenesis, progression and metastasis, and serves as a tumor diagnostic and prognostic marker as well as a potential therapeutic target." (PMID 40630623, 2025).
tumor (continued). "Compiling evidence indicates that S100A8/A9 levels are significantly elevated in tumor lesions compared to adjacent normal gastric mucosa, with strong infiltration of S100A8/A9-producing cells within tumor regions, which increases in proportion with tumor grade." (PMID 40924339, 2025). "Beyond tumor-intrinsic effects, S100A8 expression in immune cells may influence the tumor microenvironment and correlate with clinical outcomes." (PMID 41303754, 2025). "The extracellular S100A8/A9 fosters tumor growth, angiogenesis, and metastasis." (PMID 40924339, 2025). "Additionally, elevated expression of S100A8 was associated with poor prognosis in DLBCL, and inhibiting S100A8 was found to promote apoptosis and suppress tumor growth." (PMID 40270607, 2025). "Interestingly, we observed CD4+, CD8+ T cells and S100A8/9+ neutrophils within the tumor following combination treatments." (PMID 40568104, 2025). "Notably, intervening with PD1 blockade and PDT during the OPMDs stage hindered the formation of the tumor‐promoting microenvironment, resulting in decreased Treg proportion, reduced S100A8 expression, and increased Fib_Igfbp5 proportion." (PMID 38962427, 2024). "S100A8/A9, as a proinflammatory factor, activates the expression of genes related to angiogenesis and distal metastasis of tumors and participates in the establishment of the tumor metastasis microenvironment." (PMID 38641823, 2024). "Inhibition of S100A8 can promote cell apoptosis and suppress tumor growth." (PMID 38361783, 2024). "Reduction of S100A8/A9 reduces MDSC accumulation in several mouse tumor models." (PMID 38717677, 2024). "Additionally, this study reveals a previously unappreciated utility of PIM kinase inhibition in reducing S100A8/A9 expression and secretion and tumor infiltration of immunosuppressive myeloid cells in an S100A8/A9-dependent and -independent manner." (PMID 38378783, 2024). "The association between ESR1 and S100A8 and S100A9 expression levels was positive in Basal patients but negative in Her2, Luminal A, and Luminal B. S100P and S100A14 expression levels were higher in tumor tissues than in normal ones." (PMID 39594999, 2024). "al, showed that MDSCs from tumor-bearing mice, synthesize and secrete S100A8/A9, and that in vivo treatment using an anti-carboxylated glycan antibody, which was shown to bind S100A8/A9, reduced the accumulation of Gr1+CD11b+ cells (denoted as MDSCs) in the blood, spleen and lymph nodes." (PMID 39497822, 2024). "S100A8 could induce a pro-inflammatory response, including inflammatory cytokines and chemokines, and introduce the tumor-promoting effect and suppression of anti-tumor immune responses." (PMID 38361783, 2024). "We also examined the migration of tumor cells with highly expressed S100A8." (PMID 38607060, 2024). "Our findings suggest that S100A8/S100A9 act as tumor‐promoting inflammatory cytokines and may serve as prognostic indicators for OLK." (PMID 38962427, 2024). "Additionally, STAT3 was found to increase the expression of S100A8/9 proteins, which promotes the clustering of MDSCs in the tumor microenvironment (TME)." (PMID 38717677, 2024). "This led us to further investigate the potential impact of elevated intracellular S100A8 concentrations on the malignant behaviors of tumor cells and whether this mechanism involves inflammatory mediators and their corresponding receptors." (PMID 38817853, 2024). "S100A8/A9 is thought to support tumor progression via multiple mechanisms." (PMID 38378783, 2024). "Single-cell RNA sequence analysis indicated that S100A8 might be associated with features of the tumor microenvironment (TME), and immune infiltration analyses discovered that S100A8 expression was involved in TME." (PMID 38361783, 2024). "Besides being secreted by myeloid and other vascular cells, monocytes and tumor cells, S100A8/A9 is released by neutrophils upon a programmed cell-death process called NETosis." (PMID 39700646, 2024).